GFRA4 (GDNF family receptor alpha 4)
Description:
Receptor for persephin (PSPN), a growth factor that exhibits neurotrophic activity on mesencephalic dopaminergic and motor neurons. Acts by binding to its coreceptor, GFRA4, leading to autophosphorylation and activation of the RET receptor. May be important in C-cell development and, in the postnatal development of the adrenal medulla.
Tractability: Antibody: UniProt places it where antibodies can reach, with high confidence; its Gene Ontology location is reachable by antibodies, with high confidence; UniProt predicts a signal peptide or a membrane-spanning region.
Gene: Protein-coding gene on chromosome 20 (3,659,248 to 3,663,483, reverse strand). Ensembl gene ENSG00000125861.
Subcellular location: Cell membrane (Isoform GFRalpha4a); Cell membrane (Isoform GFRalpha4b); Secreted (Isoform GFRalpha4c)
Pathways (Reactome):
Developmental Biology: NCAM1 interactions; RET signaling
Signal Transduction: RAF/MAP kinase cascade
Gene Ontology:
Molecular function: glial cell-derived neurotrophic factor receptor activity; signaling receptor activity
Biological process: glial cell-derived neurotrophic factor receptor signaling pathway; nervous system development
Cellular component: extracellular region; plasma membrane; external side of plasma membrane; receptor complex
Genetic constraint (gnomAD): Loss-of-function variants: 31 observed, 15.71 expected, observed/expected ratio (o/e) 1.97, 90% interval 1.39 to 1.98. The synonymous counts are far from expectation, so gnomAD's model fits this gene poorly and the ratio says little. Missense variants: 389 observed, 257.88 expected, observed/expected ratio (o/e) 1.51, 90% interval 1.39 to 1.64. Synonymous variants: 188 observed, 127.64 expected, observed/expected ratio (o/e) 1.47, 90% interval 1.31 to 1.66.
Homologues: Orthologues: chimpanzee GFRA4 (99% identical), macaque GFRA4 (82% identical), dog GFRA4 (82% identical), guinea pig GFRA4 (73% identical), pig GFRA4 (72% identical), mouse Gfra4 (66% identical), rat Gfra4 (65% identical), zebrafish gfra4a (45% identical), zebrafish gfra4b (45% identical), tropical clawed frog gfra4 (43% identical), Caenorhabditis elegans Y69A2AR.31 (29% identical), Drosophila melanogaster Gfrl (27% identical). Paralogues in human: GFRA1 (38% identical), GFRA2 (37% identical), GFRA3 (36% identical), GFRAL (22% identical).
Diseases named in the same sentence as GFRA4 in open-access papers:
GFRA4 is named in the same sentence as 8 diseases in open-access papers, as found by Europe PMC text mining. Sharing a sentence is not in itself a finding about the gene and the disease. The quoted sentences say what the papers report.
Medullary Thyroid Cancer (3 papers, 2022 to 2025). "In contrast, medullary thyroid carcinoma (MTC), a well-differentiated NEN, has prompted the identification of a highly specific target, GFRα4, demonstrating the need for a tailored approach based on the unique molecular landscape of each NEN subtype." (PMID 41200177, 2025). "Medullary thyroid cancer (MTC) may be an excellent target for CAR T-cells therapies, given that these tumors commonly express carcinoembryonic antigen (CEA) and GDNF family receptor α4 (GFRA4)." (PMID 35936003, 2022).
breast carcinoma (1 paper, 2018). "This may reflect the extremely low expression of its co-receptor, GFRA4, in primary breast cancers, preventing PSPN from having much effect on breast cancer cells." (PMID 29608602, 2018).
disc degeneration (1 paper, 2023). "In the current study, the percentages of ARTN- and PSPN-expressing cells increased in the advanced stage of disc degeneration; however, the percentages of cells expressing their cognate co-receptors (GFRA3 and GFRA4, respectively) did not increase." (PMID 37958856, 2023).
glioma (1 paper, 2014). A benign or malignant brain and spinal cord tumor that arises from glial cells (astrocytes, oligodendrocytes, ependymal cells). "The artificial redirection of GFRA4 to the correct target results in a dramatic decrease in proliferation of glioma cells." (PMID 24466278, 2014). "A recent study showed that the GFRA4 (GDNF Family Receptor Alpha 4) are mis-located in the glioma." (PMID 24466278, 2014).
somatotroph adenomas (1 paper, 2020). "However, GFRA4 mRNA has recently been shown to be expressed in somatotroph pituitary tumors causing acromegaly." (PMID 33071961, 2020). "This has implications in pituitary pathology as demonstrated for the role of RET and GFRα4 in acromegaly tumors." (PMID 33071961, 2020).
cancer (3 papers, 2016 to 2025). A tumor composed of atypical neoplastic, often pleomorphic cells that invade other tissues. "Less information are available for six of the genes in the panel in relation to cancer namely the ITPRIP, FRMD6, CPXCR1, SLC38A9, MRPL52 and GFRA4." (PMID 27609023, 2016).
tumor (1 paper, 2024). "In preclinical studies, CAR-T cells constructed with antigens such as TSHR, ICAM-1, GFRα4, B7-H3, and CEA demonstrated anti-tumor effects." (PMID 38911868, 2024).
GFRA4 also shares sentences with these, for which no sentence is quoted: colorectal cancer (1 paper).